MUC16 (mucin 16, cell surface associated)
Diseases named in the same sentence as MUC16 in open-access papers (continued):
Sharing a sentence is not in itself a finding about the gene and the disease.
lung cancer (continued). "Additionally, MUC16 plays crucial roles in lung cancer pathogenesis, progression, and chemoresistance." (PMID 38803537, 2024). "In this study, we found that MUC16, PRX, and SDHA showed a high frequency of deleterious mutations in all primary lung cancers, and BMs inherited the genomic variations, which indicated those genes may act as lung cancer cell dissemination driver genes." (PMID 37384291, 2023). "Next, the overcoming chemoresistance by targeting MUC16 may be beneficial in lung cancer, since MUC16 overexpression influences gemcitabine and cisplatin resistance in this entity." (PMID 36230626, 2022). "Finally, MUC16 plays an important role in lung cancer development, progression, and chemo-resistance." (PMID 36552994, 2022). "The high levels of MUC16 in cell behavior experiments may be correlated with the proliferation, migration, invasion, and chemoresistance of lung cancer cells." (PMID 36552994, 2022). "MUC16 expression was found in NSCLC patients in China’s Yunnan Province who were affected by familial lung cancer (FLC) and indoor air pollution caused by coal use, as well as the study looked into the role of MUC16 in lung cancer cell proliferation, migration, invasion, and chemosensitivity." (PMID 36552994, 2022). "Furthermore, in cisplatin-resistant lung cancer cells, the expression of MUC16 was elevated, which strongly indicates the role of MUC16 in chemotherapeutic resistance in lung cancer." (PMID 36552994, 2022). "MUC16 and SMARCA4 are attractive therapeutic targets in patients at high-risk for recurrence after surgery for early-stage lung cancer and may warrant further investigation." (PMID 34880292, 2021). "These involve genes like MUC16 (CA125) whose levels relate to different stages of NSCLC, and PTK7 that is associated with lymph node metastasis as well as ALK and EGFR mutations in lung cancer." (PMID 33255394, 2020). "MUC16 could promote lung cancer progression, metastasis, and chemoresistance to cisplatin and gemcitabine via the regulation of TSPYL5 activity through JAK2/STAT3/GR axis." (PMID 32807223, 2020). "Additionally, MUC16 overexpression has functional impacts on the behavior of lung cancer cells, including increasing their cisplatin resistance, promoting their growth, and enhancing their migration and invasion capabilities." (PMID 29552305, 2018). "In the present study, MUC16 mRNA expression was increased in ∼50% of air pollution-related lung cancer samples obtained from patients residing in air-polluted regions (Xuanwei and Fuyuan, Yunnan, China), and MUC16 mRNA levels were correlated with the degree of air pollution." (PMID 29552305, 2018). "However, few studies have been conducted to clarify which MUC16 functions boost the development and progression of lung cancer." (PMID 29552305, 2018). "To study the relationship between MUC16 expression and the characteristics of lung cancer patients, we examined the MUC16 mRNA levels in the 84 NSCLC tissues and their adjacent nonmalignant tissues obtained from patients residing in air-polluted regions (Xuanwei and Fuyuan) using qRT-PCR." (PMID 29552305, 2018). "In addition, we sequenced DNA from captured MUC16 genes in air pollution-related lung cancer tissue samples." (PMID 29552305, 2018). "The presence of increased MUC16 mRNA levels in lung cancer tissues from heavily polluted areas correlates with poor prognosis, further establishing a link between MUC16 expression, environmental carcinogens, and immune system interactions in lung cancer development." (PMID 40655139, 2025).
lung cancer (continued). "Moreover, it seems that MUC16, MUC21 and MUC5B showed high mutation rates, mRNA expression and close relations to tumor immune infiltration may be still a great target for lung cancer target and immune therapy." (PMID 32807223, 2020). "MUC16, also known as CA125, is a high-molecular-weight glycosylated protein that mediates the development of breast and lung cancers by interacting with Janus kinase." (PMID 39338204, 2024). "Although MUC16 (CA125) levels were higher, the researchers showed that additional studies are required to prove CA125’s potential as a biomarker in lung cancer." (PMID 36552994, 2022). "In a study of 14 cell lines to see if MUC16 expression was present in cultured lung cancer cells, three cell lines of lung cancer (A549, 801-D, and NCI-H446) had greater MUC16 mRNA concentration than immortal human bronchial epithelial cell lines." (PMID 36552994, 2022). "Three lung cancer cell lines (A549, 801-D, and NCI-H446) expressed higher MUC16 mRNA levels compared to those of immortal human bronchial epithelial cell lines." (PMID 29552305, 2018). "MUC16 and MUC21 exhibit specific expression patterns and functions in lung cancer." (PMID 40655139, 2025). "Interestingly, MUC16 (CA125) is cleaved and shed into the bloodstream, and its serum level is thought to be a key indicator of lung cancer metastasis to the liver." (PMID 38803537, 2024). "disclosed that in lung cancer, ERO1L promotes IL6R secretion to activate the NF-κB pathway, leading to an upregulation of MUC16 gene expression, and the C-terminal of MUC16 further fosters the EMT phenotype and IL6 release, creating a positive feedback loop that exacerbates lung cancer progression." (PMID 38361923, 2024). "MUC16, also called cancer antigen 125 (CA125), is expressed in various types of brain cancer, such as glioblastoma and medulloblastoma, and nonbrain cancer, such as ovarian cancer, breast cancer, pancreatic cancer, gastric cancer, and lung cancer." (PMID 35954348, 2022). "Moreover, MUC16 was only expressed in CTCs derived from liver metastasis but were not expressed in CTCs of primary lung cancer." (PMID 38877052, 2024). "MUC16 mRNA levels in lung cancer are increased regardless of gender." (PMID 36552994, 2022). "Quantitative gene expression patterns of CXCL12, CK7, CDH1, CTNNB1, HIF1A, MUC16, TGFBR2 and CD44v6 were analyzed from CTC, exosomes and cell free RNA of lung cancer patients with and without liver metastasis." (PMID 38877052, 2024). "Besides, we calculated the 5hmC level of clinically known but nonspecific markers for lung cancer in control and tumor groups, including CEA, CA125 (MUC16), NSE (ENO2), and CYFRA21-1 (KRT19)." (PMID 30010036, 2018).
gastric cancer (54 papers, 2016 to 2025). A primary or metastatic malignant neoplasm involving the stomach. "Considering that MUC16 has been linked to the immune response in patients with gastric cancer, we anticipated that MUC16 induced glycolysis, thereby helping the NPC cells escape from immune surveillance." (PMID 39219440, 2024). "In gastric cancer research, the group with MUC16 mutations showed increased infiltration of tumour-killing cells and decreased presence of immunosuppressive cells." (PMID 38825709, 2024). "The pathogenetic role of MUC16 mutations in the prognosis of patients having cutaneous melanoma, gastric cancer, hepatocellular carcinoma, and cervical cancer has been well reported." (PMID 37932988, 2023). "Some researchers use tissue biomarkers (TFF2, mir-124a-3p, etc.), innovative blood biomarkers, and other low-cost markers (CEA, CA19-9, MUC16, etc.)to predict and evaluate the risk of gastric cancer." (PMID 36052291, 2022). "MUC16 has also been reported to be associated with prognosis and immunotherapy efficiency in gastric cancer." (PMID 34306002, 2021). "In gastric cancer, the occurrence of MUC16 gene mutations is correlated with tumor mutational burden and associated with better OS." (PMID 34831445, 2021). "have reported that MUC16 mutations were strongly correlated with immune-related pathways in gastric cancer." (PMID 34650549, 2021). "In contrast to MUC4, mutated MUC16 may serve as a prognostic marker for favorable survival outcomes in gastric cancer." (PMID 39338204, 2024). "Building upon this observation, it is worth highlighting that prior research has unequivocally established the significance of TTN and MUC16 gene mutations in shaping the prognosis of gastric cancer, while also serving as pivotal biomarkers for guiding the administration of ICIs." (PMID 38066437, 2023). "In addition, mutated MUC16 was shown to improve the survival prognoses in patients with skin cutaneous melanoma, as well as in patients with gastric cancer." (PMID 37504272, 2023). "In addition, the group of patients with MUC16 mutation had better survival outcomes in gastric cancer." (PMID 36291742, 2022). "We observed MUC16 mutation in our dataset, similar to recent reports in gastric cancers." (PMID 33664766, 2021). "MUC16 was recently reported to be associated with the prognosis of gastric cancer." (PMID 33005171, 2020). "Similarly, the MUC4/MUC16/MUC20high group in stomach cancer showed a median survival of 762 days whereas the low risk had a median survival of 1811 days." (PMID 30236127, 2018). "In other organs, the MUC4/MUC16/MUC20high group was associated with an increased hazard ratio and reduced overall survival in bladder cancer, colon cancer, lung adenocarcinoma, lung squamous adenocarcinoma, skin cancer, stomach cancer." (PMID 30236127, 2018). "Besides, IDH1 and MUC16 mutations are associated with an improved prognosis in gastric cancer." (PMID 36900401, 2023). "Furthermore, a significant correlation between the MUC16 mutation with tumour mutational burden and microsatellite status was shown in patients with gastric cancer, colorectal cancer, and melanoma which signifies the used of immune checkpoint inhibitor (ICI) in the treatment regimen." (PMID 36866106, 2022). "For example, MUC16 was mutated in 38.4% of gastric cancer (GC) patients, and was associated with higher TMB and good immune response." (PMID 35568842, 2022). "Moreover, MUC16 mutations, the most frequently mutated in this analysis, have been previously demonstrated to be associated with a higher tumor mutational burden and superior survival outcomes in gastric cancer patients." (PMID 31242667, 2019).
gastric cancer (continued). "Out of the 276 total protein assays, MUC16 was clearly the most useful (mean decrease Gini > 2.0) for predicting prometastatic gastric cancer as plotted with the highest mean decrease Gini." (PMID 38956143, 2024). "In this study, we found the potential of MUC16 as a novel marker for predicting metastasis in gastric cancer and underscored its superiority compared to traditional markers such as CEA and CA19-9." (PMID 38956143, 2024). "In the TCGA stomach cancer tissue data, the mRNA expression level of MUC16 was significantly increased according to stage." (PMID 38956143, 2024). "IGF2BP3 and MUC16 are overexpressed in gastric cancer cell lines, and they are significantly upregulated in diffuse gastric cancer cell lines and SRCC cell lines that are closely related to diffuse gastric cancer." (PMID 36450891, 2023). "Two genes were identified using immunohistochemistry (IHC), IGF2BP3 and MUC16, which specifically expressed in diffuse-type-related gastric cancer cell lines, and its knockdown inhibits PI3K-AKT pathway activity." (PMID 36450891, 2023). "In some literatures, MUC16 mutation is associated with better prognosis and higher TMB in gastric cancer, while TTN mutation is associated with immune checkpoint blockade in solid tumors." (PMID 37274740, 2023). "Previous studies demonstrated that MUC16 mutation correlated with better prognosis and higher TMB in gastric cancer." (PMID 37296697, 2023). "MUC16 was reported to associate with a higher TMB and a better immunotherapy outcome in gastric cancer." (PMID 33579226, 2021). "We propose the MUC4/MUC16/MUC20high signature as a marker of poor prognostic for pancreatic, colon and stomach cancers." (PMID 30236127, 2018). "This combination is associated with a poorer overall survival in different cancers including pancreatic, colon and stomach cancers suggesting MUC4/MUC16/MUC20 as a poor prognostic signature for these cancers." (PMID 30236127, 2018). "We showed that the combination of MUC4, MUC16 and MUC20 signature is associated with statistically significant reduced overall survival and increased hazard ratio in pancreatic, colon and stomach cancer." (PMID 30236127, 2018). "(A) Overall survival of MUC4/MUC16/MUC20 high and low risk groups in bladder cancer, colon cancer, lung adenocarcinoma, lung squamous adenocarcinoma, skin cancer and stomach cancer." (PMID 30236127, 2018). "In diagnosing PM, preoperative MUC16 serum levels in gastric cancer patients showed sensitivities ranging from 38.6 to 55 % and specificities between 93.9 and 100 %." (PMID 27074785, 2016). "Our findings align with a retrospective prognostic analysis of 437 samples from patients with gastric cancer, showing that presence of MUC16 mutations were associated with better prognosis when compared to patients without MUC16 mutations." (PMID 39240165, 2024). "Mutant MUC16 was also found to result in a better prognosis in gastric cancer and low-grade glioma." (PMID 38825709, 2024). "Additionally, MUC16 expression levels in cancer tissues were significantly increased with increasing stage in TCGA stomach cancer public data." (PMID 38956143, 2024). "Besides, the combined mutation status of MUC4, MUC16, and TTN showed the potential to predict TMB and immunotherapy efficacy in gastric cancer and pan cancer." (PMID 37814942, 2023). "As for TTN and MUC16, the study of gastric cancer or ferroptosis is still blank." (PMID 34977116, 2021). "Somatic mutations of MUC16 and TNN correlated with better survival in gastric cancer." (PMID 34307129, 2021). "Our previous study reported the association of MUC16 mutations with high TML and favorable outcome in gastric cancer (GC)." (PMID 32491995, 2020).
gastric cancer (continued). "Among them, MUC16 and MUC20 membrane-bound mucins and their combination MUC4/MUC16/MUC20 is associated with a poorer overall survival in different cancers including pancreatic, colon and stomach cancers suggesting MUC4/MUC16/MUC20 as a poor prognostic signature for these cancers." (PMID 30236127, 2018). "To validate the findings in human gastric cancer specimens, we first analyzed the expression levels of IGF2BP3 and MUC16 in 13 GLP and 30 gastric cancer tissues using immunohistochemistry." (PMID 36450891, 2023). "To validate the findings of WTS in GLP tissues, we analyzed the expression of IGF2BP3 and MUC16 in the human gastric epithelial cell line GES1 and the human gastric cancer cell lines AGS (intestinal-type), NUGC4 (diffuse-type), and KATO III (signet ring cell carcinoma, SRCC)." (PMID 36450891, 2023).
ovarian tumor (37 papers, 2006 to 2025). "MUC16 expression is a hallmark of ovarian neoplasms of serous origin, widely used in serum detection assays as a marker of disease progression and response to therapy in the OVCA setting." (PMID 30011875, 2018). "MUC16-knockdown ovarian tumor cells were more susceptible to lysis by primary NK cells than MUC16 expressing controls." (PMID 20089172, 2010). "The differentiated subtype was associated with high expression of ovarian tumor markers (MUC1 and MUC16) and the secretory fallopian tube marker SLPI, suggesting a more mature stage of development." (PMID 40953111, 2025). "The interaction of MUC16 with mesothelin has been shown to mediate cell adhesion and facilitate peritoneal metastasis of ovarian tumors." (PMID 38197671, 2024). "This antigen is overexpressed on most ovarian tumor cells and is a residue of MUC-16 after CA-125 cleavage." (PMID 38927974, 2024). "Here, we have constructed CAR T cells based on mesothelin polypeptide sequences that bind MUC16 to effectively eliminate MUC16-expressing ovarian cancer tumor cells and stem cells in vitro, as well as to eliminative ovarian tumor xenografts in vivo." (PMID 38637885, 2024). "In this study, we report the results of long-read sequencing of mRNA from three cancer cell lines and three ovarian tumors which enabled us to propose a revised molecular model of MUC16." (PMID 38197671, 2024). "C4/Differentiated tumors express higher levels of ovarian tumor markers such as MUC16 (CA125) compared to the other subtypes, sharing features of borderline serous tumors." (PMID 37858159, 2023). "In ovarian tumors, such proteins include MUC-1, mucin-16 (MUC-16), and tumor-associated glycoprotein 72 antigen (TAG72)." (PMID 37420216, 2023). "Ovarian tumor cells impair the formation of immunological synapses with NK cells by expressing the glycoprotein mucin 16 (MUC16), which has anti-adhesive properties." (PMID 34768814, 2021). "The stimulation of MUC16 release by cytokines in various cancer cell lines, including, endometrial, breast and ovarian tumor cells have also been variable." (PMID 31039761, 2019). "As has been shown in previous studies, we also detected a down-regulation of MUC16 expression in ovarian tumors post-treatment as compared to the pretreatment stage." (PMID 30287783, 2018). "The proliferative subtype was identified by the overexpression of transcription factors HMGA2 and SOX11, proliferation marker genes such as MCM2 and PCNA, and underexpression of MUC1 and MUC16, which are known ovarian tumor marker genes." (PMID 25611546, 2015). "Oregovomab, (B43.13, OVAREX) is a mouse anti-MUC16 antibody developed for the in vivo detection of ovarian tumors." (PMID 24886523, 2014). "We focus on the increasing body of literature describing the biological role of MUC16 in the progression and metastasis of ovarian tumors." (PMID 24886523, 2014). "NK cells preferentially target ovarian tumor cells that express low levels of MUC16 on their cell surface." (PMID 24886523, 2014). "It will be interesting to determine the efficacy of treatment regimens that combine anti-MUC16 antibodies with agents that can inhibit MUC16 release in controlling the growth of ovarian tumors." (PMID 24886523, 2014). "Expression of low levels of MUC16 strongly correlated with an increased number of conjugates and activating immune synapses between ovarian tumor cells and primary naïve NK cells." (PMID 20089172, 2010). "Our results indicate that MUC16-mediated inhibition of immune synapse formation is an effective mechanism employed by ovarian tumors to evade immune recognition." (PMID 20089172, 2010). "We have now also demonstrated that MUC16 protects the ovarian tumor cells by sterically blocking the NK cells from forming immune synapses with the cancer cells." (PMID 20350313, 2010).